CTLA4 (cytotoxic T-lymphocyte associated protein 4)
Diseases named in the same sentence as CTLA4 in open-access papers (continued):
Sharing a sentence is not in itself a finding about the gene and the disease.
lymphoma (89 papers, 2010 to 2026). A malignant (clonal) proliferation of B- lymphocytes or T- lymphocytes which involves the lymph nodes, bone marrow and/or extranodal sites. "In the context of lymphoma, elevated CTLA-4 expression is linked to an increased proportion of lymphoma stem cells and enhanced proliferation and invasion of lymphoma cells via the TGF-β pathway." (PMID 37784157, 2023). "A previous study addressing the genetic cause of CVID in 10 patients with lymphoma revealed a heterogeneous genetic background, including a patient with CTLA4-insufficiency and one with APDS as a consequence of a monoallelic gain-of-function variant in PIK3CD." (PMID 35250968, 2022). "Immune checkpoint inhibitors targeting the co-inhibitory molecules cytotoxic T-lymphocyte-associated protein 4 (CTLA-4) and PD-1 have been approved for the treatment of various solid tumors and lymphoma." (PMID 36405718, 2022). "In other studies, however, CTLA4 rs231775 had been linked to lymphoma risk." (PMID 41155207, 2025). "CTLA4 rs231775 may act as a risk factor for colorectal and thyroid cancers, while conversely serving as a protective factor against breast, liver, pancreatic and malt lymphoma." (PMID 40862794, 2025). "We previously analyzed the clinical impact of CTLA4 rs231775 in the same lymphoma cohort which prompted a stratified analysis in all genetic combinations of LAG3 rs870849 and CTLA4 rs231775 in the current study." (PMID 41155207, 2025). "The PD-1/PD-L1 axis is central to lymphoma immunotherapy: PD-1/PD-L1 blockade counters tumor immune evasion, whereas CTLA-4 inhibition enhances early T-cell activation in lymphoid tissues." (PMID 41357215, 2025). "In the previous study, we presented evidence for a favorable clinical outcome to CAR-T cell therapy in lymphoma patients carrying a germline CTLA4 rs231775." (PMID 41155207, 2025). "ADU-S100 was tested in combination with α-PD-1 spartalizumab (NCT03172936) and anti-CTLA-4 antibody (α-CTLA-4) ipilimumab (NCT02675439) in patients with solid tumors or lymphomas, respectively." (PMID 39871312, 2025). "CTLA4 is highly expressed on Tregs and inhibition has shown promising results in various solid cancers and in other types of lymphomas but with few clinical investigations in MCL." (PMID 39001353, 2024). "Among IEI-associated genes,7,9NFKB2,26PIK3CD, STAT1,27PALB2, SH2D1A,28TNFRSF13B,10MSH6, CTLA4 genes had previously been reported in lymphoma or hematological malignancies genomic studies or are lymphoma susceptibility genes." (PMID 38547930, 2024). "ADU-S100 was evaluated in a phase I clinical trial involving 47 patients with advanced/metastatic solid tumors or lymphomas, either alone or in combination with ipilimumab, an immune checkpoint inhibitor that targets CTLA-4 (NCT02675439)." (PMID 38502231, 2024). "EVs derived from lymphomas increase CTLA4 expression on CD8+ T cells, converting them into regulatory CD8+ T cells that perform immunosuppressive functions and secrete the inhibitory cytokines IL10 and TGF-β98." (PMID 39528800, 2024). "Our results demonstrate that combining CpG-Stat3 siRNA with CTLA4 or PD-1 antibody suppressed A20 lymphoma tumor growth more effectively than either CpG-Stat3 siRNA or CTLA4 or PD-1 antibody alone." (PMID 39618825, 2024). "The first study that documented CTLA-4 expression in tumor cells, published in 1997 in human lymphomas, suggested that CTLA-4 promotes tumor escape by inhibiting anti-tumor responses but not the proliferation of malignant lymphocytes." (PMID 38611048, 2024). "CTLA-4 is an inhibitory surface receptor with significantly elevated expression in lymphoma tissues and is an indicator for the early diagnosis and clinical treatment of lymphoma." (PMID 39464313, 2024). "EVs carrying lymphoma surface antigens can preferentially bind to chimeric antigen receptor-modified T cells that are used in therapy, increasing CTLA4 expression on their surface and impairing their tumor-killing ability." (PMID 39528800, 2024).
lymphoma (continued). "CTLA-4 inhibitors, DNA methyltransferase inhibitors, chimeric antigen receptor T-cell therapy are also being explored in relapsed/refractory lymphomas, and there is hope for future use in extranodal lymphomas as well." (PMID 37718386, 2023). "CTLA-4 was also upregulated ~2–2.5-fold in T cells of healthy controls compared to patients with indolent and aggressive lymphoma." (PMID 36359267, 2022). "Since HSP and immune checkpoint expression are associated with T cell activation, we next sought to analyze the effect of HSP90 inhibitors alone or in combination with PD-1 or CTLA-4 inhibitors on T cell degranulation response in lymphoma patients." (PMID 36359267, 2022). "For example, cytotoxic T lymphocyte-associated antigen 4 (CTLA4) can activate TYK2 by subsequent phosphorylation, resulting in the promotion of lymphoma cell proliferation." (PMID 36104718, 2022). "CTLA-4 significantly promoted the proliferation and invasion of lymphoma cells, and TGF-β neutralization can significantly block these effects of CTLA-4." (PMID 34553071, 2021). "In summary, CTLA-4 promoted lymphoma progression by increasing the number of tumor stem cells and Treg cells." (PMID 34553071, 2021). "Numerous immunotherapeutic agents targeting PD-1, PD-L1, CTLA-4 have revolutionized treatment for cancer, including lymphoma." (PMID 34327425, 2021). "Compared to the control group, the proliferation and invasion of lymphoma cells in the CTLA-4 inhibition group were significantly reduced." (PMID 34553071, 2021). "The proportion of Treg cells and T cells in the CTLA-4 group was 0.96 and 39.38%, and the differences were statistically significant when compared with the lymphoma group." (PMID 34553071, 2021). "Many studies have reported that CTLA-4 is highly expressed in multiple lymphoma types, including DLBCL, Hodgkin’s lymphoma, and follicular lymphoma." (PMID 34553071, 2021). "CTLA-4 can increase the proportion of lymphoma stem cells and promote the proliferation and invasion of lymphoma cells." (PMID 34553071, 2021). "Cytotoxic T lymphocyte-associated antigen 4 (CTLA-4) can inhibit antitumor immunity and promote cancer progression, but its role and mechanism in lymphoma are still unclear." (PMID 34553071, 2021). "In the same study, using a co-culture system, the authors showed that A20 lymphoma cells can internalize CD86 expressed on APCs via CTLA-4." (PMID 35071240, 2021). "In vitro experiment showed that CTLA-4 increased the ratio of lymphoma stem cells, and proliferation and invasion of lymphoma cells through TGF-β pathway." (PMID 34553071, 2021). "In conclusion, CTLA-4 promoted DLBCL progression through lymphoma stem cell enrichment and immunosuppression." (PMID 34553071, 2021). "Correlation analysis showed that the expression of CTLA-4 was positively correlated with the proportion of Treg cells in lymphoma." (PMID 34553071, 2021). "Correlation analysis showed that CTLA-4 expression positively correlated with CD44+ cell in lymphoma tissue and regulatory T (Treg) cells in lymphocytes." (PMID 34553071, 2021). "Lymphoma cells with higher CTLA-4 expression can induce the proliferation of Treg cells, which can recruit more immunosuppressive cells into the tumor and suppress the anti-tumor immune response." (PMID 34553071, 2021). "Our study found that CTLA-4 can increase the number of lymphoma stem cells and enhance the proliferation and invasion ability of lymphoma cells through the TGF-β pathway." (PMID 34553071, 2021). "There were two trials involving BsAbs for lymphoma in China to date, with one focusing on anti-cytotoxic T lymphocyte associate protein-4 (CTLA-4) /PD-1 (NCT04444141) and one on anti-CTLA-4/PD-L1 (NCT03733951)." (PMID 34327425, 2021). "Compared to the lymphoma group, the proportion of Treg cells decreased significantly in the CTLA-4 inhibition group, while the proportion of T cells increased significantly." (PMID 34553071, 2021).
lymphoma (continued). "Although most clinical studies of blocking PD-1 and CTLA-4 with humanized monoclonal antibodies are directed at solid tumors and lymphoma, PD-1 and CTLA-4 also play a role in leukemia, GVL and GVHD." (PMID 31616632, 2019). "Flow cytometric analysis revealed that the expression of PD-1 on CD4+ peripheral and tumor infiltrating lymphocytes and CTLA-4 on CD4+ peripheral lymphocytes was significantly higher in the lymphoma group than in the control group." (PMID 30040869, 2018). "The proportion of CTLA-4+ cells in CD4+ lymphocyte populations obtained from PBMCs was significantly higher in the lymphoma group (1.40% ± 0.92%) than in the control group (0.62% ± 0.26%, P = 0.018)." (PMID 30040869, 2018). "In this review, we demonstrate actual knowledge on immune checkpoint function and its impact on development of new modality of antineoplastic treatment, using, for example, anti-CTLA-4 or PD-1/PD1 ligand (PD-L1) monoclonal antibodies in malignant lymphomas." (PMID 29850620, 2018). "We found that CTLA-4 expression on CD4+ T cells obtained from PBMCs was significantly higher in the lymphoma group than in the control group." (PMID 30040869, 2018). "In these lymphoma samples, significantly higher expression of CTLA-4 was observed on CD4+ lymphocytes obtained from PBMCs." (PMID 30040869, 2018). "In summary, this study indicates that PD-1 expression is up-regulated on both peripheral and tumor infiltrating T cells and that CTLA-4 expression is up-regulated on CD4+ T cells from peripheral blood obtained from dogs with B cell high grade lymphoma." (PMID 30040869, 2018). "In this connection, the repression of the immune checkpoint inhibitor CTLA-4 by DNA methylation in ALCL can provide appropriate justification for the epigenetic therapy with the objective of re-sensitizing lymphoma cells to checkpoint regulation." (PMID 28771164, 2017). "Both latently and lytically infected lymphoma cells were decreased in EBV-infected cord blood-engrafted animals treated with the PD-1/CTLA-4 blocking antibodies." (PMID 27186886, 2016). "To further examine potential mechanisms by which PD-1/CTLA-4 blockade promotes T cell infiltration of lymphomas in this model, we determined if immune checkpoint blockade increased the number of high endothelial venules (HEVs) in tumors." (PMID 27186886, 2016). "Our results suggest that PD-1/CTLA-4 blockade increases the ability of T cells to infiltrate EBV-induced lymphomas, and to become highly activated (as measured by NFATC1 nuclear translocation)." (PMID 27186886, 2016). "In contrast, lymphomas of similar size in EBV-infected animals treated with PD-1/CTLA-4 blockade had many more infiltrating CD8-positive and well as CD4-positive T cells, such that T cells often outnumbered the B cells in tumor infiltrates." (PMID 27186886, 2016). "Lymphomas in PD-1/CTLA-4 treated animals expressed more RANTES than did the lymphomas in untreated animals." (PMID 27186886, 2016). "Expression levels of B7-1 (CD80) and B7-2 (CD86), ligands for the activation receptor CD28 and inhibitory receptor CTLA-4 (CD152) on T cells, vary between different models and subtypes of lymphoma." (PMID 25941795, 2015). "In lymphoma, IL-10 -3575A and TNF -308G increase the risk of DLBCL, and CTLA-4 + 49 A > G increases the risk of MALT lymphoma." (PMID 26108796, 2015). "CTLA-4 inhibits anti-tumor immune response and is closely related to the malignancy of lymphoma." (PMID 39464313, 2024). "This study showed that PD-1/CTLA-4 blockade can enhance the ability of cord blood T cells to control EBV-induced lymphoma growth and suggested that PD-1/CTLA-4 blockade may be useful in the treatment of some human EBV-induced diseases." (PMID 35559250, 2022). "The CTLA-4/CD3-ratio also showed differences between different tumor categories: Lowest values were found in lymphomas (5 ± 7) and germ cell tumors (8 ± 24) while highest values were seen in melanocytic (25 ± 43) as well as epithelial tumors (18 ± 48, p < 0.0001)." (PMID 35091676, 2022).
lymphoma (continued). "In conclusion, while combining PD-1 and CTLA-4 blockade (nivo/ipi) or PD-1 and KIR blockade (nivo/liri) is feasible in patients with advanced lymphoma and MM, the combination of nivo/ipi appears to be associated with increased but manageable toxicity over that expected with single-agent nivolumab." (PMID 32601377, 2021). "Animal experiments showed that CTLA-4 can promote transplanted lymphoma growth." (PMID 34553071, 2021). "Correlation analysis results showed that CTLA-4 expression was positively correlated with the proportion of CD44+ cells in lymphoma, indicating that CTLA-4 may have a certain correlation with tumor stem cells." (PMID 34553071, 2021). "ELISA results showed that CTLA-4 could significantly increase the level of TGF-β in lymphoma cell, while the level of TGF-β in CTLA-4 siRNA group was significantly decreased." (PMID 34553071, 2021). "In this study, CTLA-4 expression on peripheral CD4+ and CD8+ lymphocytes and CD4+ lymphocytes obtained from LNCs was found to be associated with poor prognosis in canine B cell high grade lymphomas." (PMID 30040869, 2018). "Combined inhibition of PD1 or PD-L1- and CTLA4-mediated suppression of anti-lymphoma immunity seems supported by the finding that CTLA4 significantly increased during treatment with nivolumab and ipilmumab and remained so after the stop of treatment with this drug (lane e)." (PMID 29755699, 2018). "Blocking PD-1/CTLA-4 inhibits Epstein-Barr virus(EBV)-induced lymphoma growth." (PMID 28408983, 2017). "The reduced size of EBV-induced lymphomas in PD-1/CTLA-4 antibody treated cord-blood humanized mice suggests that cord blood-derived human T cells may be better able to infiltrate lymphomas and kill tumor cells following PD-1/CTLA-4 blockade." (PMID 27186886, 2016). "Furthermore, increased NFATC1 expression, as well translocation of NFATC1 to the nucleus, was observed in the smaller lymphomas in PD-1/CTLA-4 treated animals." (PMID 27186886, 2016). "In addition, we found that enhanced T cell infiltration of PD-1/CTLA-4 ab treated lymphomas was accompanied by a higher number of intra-tumor high endothelial venules (HEVs)." (PMID 27186886, 2016). "Of note, although larger lymphomas were much less common in the PD-1/CTLA-4 treated versus untreated animals, when they did occur in the treated animals they had much reduced T cell infiltration and NFATC1 nuclear accumulation in comparison to the smaller tumors." (PMID 27186886, 2016). "Thus, an increased number of intra-tumor HEVs in the PD-1/CTLA-4 treated animals likely plays a role in promoting enhanced T cell infiltration of lymphomas." (PMID 27186886, 2016). "Furthermore, we show that the combination of CTLA-4 and PD-1 blockade strikingly reduces the size of lymphomas induced by a lytic EBV strain (M81) in this model, and that this anti-tumor effect requires T cells." (PMID 27186886, 2016). "In addition, we determined if enhanced T cell infiltration in lymphomas of PD-1/CTLA4-treated animals was associated with increased expression of the T cell chemokine, RANTES, within lymphomas." (PMID 27186886, 2016). "Importantly, we find that the combination of PD-1 and CTLA-4 blockade decreases the growth of EBV-induced lymphomas in this model, and demonstrate that this anti-tumor effect requires T cells and enhances their responses to EBV." (PMID 27186886, 2016). "In addition, a survival study confirmed that the length of survival in EBV-infected cord blood humanized mice was significantly longer in PD-1/CTLA-4 treated animals, although all animals eventually succumbed to lymphoma." (PMID 27186886, 2016). "While the BTLA-HVEM pathway as a mechanism of immune escape is only beginning to be studied in the context of lymphoma, it may be an actionable target similar to the CTLA-4 inhibitory pathway." (PMID 25941795, 2015).
lymphoma (continued). "Our study found that compared to normal lymphoid tissue, CTLA-4 expression in lymphoma tissues was significantly increased and was closely related to the malignant degree of lymphoma, indicating that CTLA-4 could be used as an indicator for early diagnosis and clinical treatment of lymphoma." (PMID 34553071, 2021). "Moreover, CTLA-4 enhanced the proliferation of Treg cells induced by lymphoma cells." (PMID 34553071, 2021). "So far, it was reported that CD80 and CD86, physiological ligands for CTLA-4 expression, may be seen in patients with T cell lymphomas in the cell of dendritic system, a subset of germinal-center B cells and B immunoblasts in lymphoma nodes and Reed-Sternberg cells." (PMID 29850620, 2018). "In another study, the growth of a humanized lymphoma in mice induced by the injection of EBV (strain 81)-infected human cord blood was assessed following the simultaneous blockade of PD-1 and CTLA-4." (PMID 35559250, 2022). "When compared with the lymphoma group, the proportion of CD44+ cells and the expression of TGF-β in the CTLA-4 inhibition group decreased significantly." (PMID 34553071, 2021). "The purpose of this study is to investigate the expression of CTLA-4 in DLBCL and to explore its correlation with tumor stem cells and Treg cells, so as to provide theoretical support for immunotherapy of lymphoma." (PMID 34553071, 2021). "Combined ICB with anti-CTLA-4 and anti-PD-1 mAb protected 18% to 30% of λ-MYC mice from lymphomas for at least 200 days." (PMID 32165639, 2020). "ICB with PD-1/PDL-/CTLA4 inhibitors and CAR-T therapy targeting CD19+ leukemia/lymphoma have forever changed the landscape of cancer therapeutics." (PMID 31186046, 2019). "We elucidate the pathophysiological role of immunosuppressive networks in lymphomas, ranging from changes in the cellular microenvironment composition to distinct signaling pathways such as PD1/PDL1 or CTLA4/B7/CD28." (PMID 29564225, 2018). "A combination of anti-PD-1 and anti-CTLA-4 therapies produced an enhanced ability to control EBV infection, leading to reductions in lymphomas, increased EBV effector responses, and decreases in EBV-infected B cells." (PMID 28981470, 2017). "We also found that PD-1/CTLA-4 blockade reduced the number of latently infected, as well as lytically infected, EBV-positive lymphoma cells in this humanized mouse model." (PMID 27186886, 2016). "Here we demonstrate that treatment of EBV-infected cord-blood humanized NSG mice with the combination of both CTLA-4 and PD-1 blocking antibodies strikingly decreases the growth rate of EBV-induced lymphomas, and increases the length of survival in mice." (PMID 27186886, 2016). "For lymphoma patients, there are a variety of potential targets, such as T-cell markers (CD3, CD4, and CD8), B-cell markers (CD19 or CD20), and immune checkpoints (PD-1, PD-L1, or CTLA-4)." (PMID 37189191, 2023). "For instance, the TIME in cHL benefits immune checkpoint blockade therapy, as this lymphoma features extensive non-malignant immune infiltrate with CTLA-4+ T-cells, in addition to the very scarce neoplastic HRS cells that commonly express PD-Ls." (PMID 35327589, 2022). "In the past decade, ICB targeting PD-1, PD-L1, or CTLA-4 has proven effective against a variety of solid tumor malignancies as well as Hodgkin lymphoma, and there was optimism that ICB would be successful in GCB lymphomas as well." (PMID 35071240, 2021). "CTLA-4 significantly increased the proportion of CD44+ CD34+ cells in lymphoma cells, and TGF-β neutralization could significantly block this effect of CTLA-4." (PMID 34553071, 2021). "Having previously shown that multiple mechanisms, which also involve NK cells, are elicited by ICB therapy, we now asked the question whether DCs contribute to the therapeutic potential of anti-CTLA-4 and anti-PD-1 mAbs in the λ-MYC lymphoma model." (PMID 33141285, 2021).